GHRH (growth hormone releasing hormone)
Diseases named in the same sentence as GHRH in open-access papers (continued):
Sharing a sentence is not in itself a finding about the gene and the disease.
cancer (continued). "A.V.S., R.C., R.M.J. and M.M. are listed variously as co-inventors on United States patents regarding the use of GHRH analogs in cancer, fibrosis and sarcoid, which are assigned to the University of Miami and the Department of Veterans Affairs." (PMID 33096674, 2020). "Accordingly, various studies showed that GHRH and GHRH antagonists can influence the inflammatory and reduction/oxidation (redox) status in cancer and other tissues." (PMID 31959947, 2020). "GHRH peptide and GHRH-R are expressed in normal extra-pituitary tissues, including tumors, cancer cell lines, and immune cells." (PMID 33096674, 2020). "This inhibitory action of GHRH antagonists on IGF-1 levels in serum has been demonstrated by our group in nude mice bearing various human cancers." (PMID 29983893, 2018). "Antagonists of GHRH have been shown to inhibit the cell growth and behavior of multiple types of cancer cells." (PMID 28032599, 2017). "In current present study, we further showed that the treatment of human cancer cells with a GHRH antagonist inhibited the cell migration and invasion." (PMID 28032599, 2017). "In vitro and in vivo studies have demonstrated that GHRH antagonists inhibit the growth of several cancers." (PMID 27448980, 2016). "Schally's team also were the first to describe GHRH antagonists and their possible application for cancer treatment." (PMID 27774107, 2016). "For the past 25 years the antitumor properties of GHRH antagonists have been studied on cancer cell lines from breast, prostate, pancreas, colon, lung, ovarian, brain, and lymphocyte." (PMID 27774107, 2016). "GHRH peptide, first found in pancreatic and carcinoid tumors, was subsequently also detected in many other cancers." (PMID 27494841, 2016). "This study illustrates the potential benefits of using GHRH antagonists for the treatment of cancers that are highly resistant to cytotoxic agents such as doxorubicin." (PMID 25593995, 2014). "This study illustrates the benefits of using GHRH antagonists for the treatment of cancers which are highly treatment-resistant." (PMID 22941871, 2012). "In vitro and in vivo proliferation of various human cancers is suppressed by antagonistic analogs of GHRH (referred to as “GHRH antagonists”)." (PMID 22941871, 2012). "Many studies were performed on the effects of the GHRH antagonists on different experimental cancers or human cancer cell lines." (PMID 20509930, 2010). "Antagonists of growth hormone-releasing hormone (GHRH) are being developed for the treatment of various human cancers." (PMID 20509930, 2010). "Antagonists of growth hormone-releasing hormone (GHRH) are being developed for the treatment of various cancers." (PMID 20509930, 2010). "In larger animals, we have previously shown that GHRH treatment followed by EP can dramatically improve the conditions for companion animals with cancer, resulting in an extended life span with a greatly improved quality of life." (PMID 19149896, 2009). "A band of 45 KDa which reflects the production of pre-pro GHRH was detected in all the cancer cell lines examined." (PMID 18506184, 2008). "The proliferation of T47Ds, MDA-MB-468, MDA-MB-435, LNCaP and NCI H838 cancer cell line was also inhibited by 31–37%, 26–31%, 31–38%, 34–41%, 37–42% respectively after exposure to GHRH antagonist JMR-132 at doses of 0.1 and 1 μM." (PMID 18506184, 2008). "The antitumour activity of our GHRH antagonists is especially important oncologically because of the wide expression of the intrinsic GHRH, pGHRH-R and SVs of GHRH-R in various cancers." (PMID 18506184, 2008). "Biologically active GHRH was detected by RIA in the conditioned medium of all the cancer cell lines, except for MCF-7." (PMID 18506184, 2008).
cancer (continued). "One way to elucidate the role of GHRH in the pathogenesis of cancer is to inhibit its gene expression." (PMID 18506184, 2008). "We then inhibited the intrinsic production of GHRH in these cancer cell lines using si-RNA, specially designed for human GHRH." (PMID 18506184, 2008). "In the present study, we first examined the expression of pre-pro GHRH by western blot in human cancer cell lines." (PMID 18506184, 2008). "Thus, GHRH antagonists can directly block the tumoral receptors for GHRH and prevent the activation of the autocrine/paracrine GHRH in cancers." (PMID 39934495, 2025). "However, in vivo, GHRH agonists inhibit growth of human cancers xenografted into nude mice and downregulate pituitary and tumoral GHRH-Rs." (PMID 39934495, 2025). "In vitro, GHRH agonists can stimulate growth of human cancer cells and upregulate GHRH-Rs." (PMID 39934495, 2025). "There is very limited information on these effects of GHRH-related analogs in cancer cells." (PMID 38957466, 2024). "However, published data and information on GHRH and SVs of GHRH-Rs in pediatric cancers are very limited." (PMID 39201517, 2024). "Recapitulating pre-clinical evidence, GHRH antagonists (GHRH-Ant) have significant anti-cancer activity across experimental human AML cell lines in vitro and in vivo and demonstrate significant inhibition of cancer in drug resistant analogs of leukemic cell lines as well." (PMID 39417961, 2024). "Moreover, various studies showed that these potent GHRH antagonists with strong anticancer effects were able to inhibit the growth of several human cancer models in vivo." (PMID 39201517, 2024). "This has been corroborated by literature illustrating mRNA for GHRH peptides, as well as mRNA for the GHRH-R and up to four different splice variants, SV1 being the most common form, both in vitro and in vivo across multiple cancer models." (PMID 39417961, 2024). "Notably, growth hormone-releasing hormone (GHRH) receptor antagonist MIA-602 has been shown to impede the growth of various human cancer cell lines, including AML." (PMID 38588464, 2024). "The ability of GHRH agonists to modulate both endocrine and extra-endocrine pathways makes them versatile tools for the treatment of a variety of diseases, from metabolic disorders to cancer." (PMID 39592529, 2024). "Given the role of GHRH in multiple cancer types, it is possible that GHRH antagonists may offer an alternative treatment approach for AML as well as drug-resistant AML, which may circumvent the side effects associated with standard chemotherapy." (PMID 38588464, 2024). "The antinflammatory behavior of GHRH antagonists in both cancer and other diseases is well known." (PMID 37649486, 2023). "Moreover, an autocrine/paracrine stimulatory loop formed by locally produced GHRH and its receptors, particularly the splice variant 1 (SV1), promotes the growth of many cancers, a mechanism that can be blocked by GHRH antagonists." (PMID 37649486, 2023). "The GHRH peptide has also been identified in samples of surgical tissues from various types of malignancies such as breast, endometrial, ovarian, colorectal, gastric, pancreatic, lung cancers, lymphomas, and other related human cancer cell lines." (PMID 37370714, 2023). "In addition to its neuroendocrine function, growth-hormone-releasing hormone (GHRH) acts as an autocrine/paracrine growth factor in various cancers, including gastrointestinal cancers." (PMID 36979698, 2023). "Moreover, the inhibitory role of GHRH antagonists on these inflammatory pathways has been demonstrated in different types of experimental cancers, as well as inflammatory diseases." (PMID 36232554, 2022). "The beneficial oncological effects of these antagonists in experimental cancer treatment can be attributed to the suppression of pituitary-hepatic IGF-I axis and the direct inhibition through the binding of GHRH antagonists to pituitary GHRH-R and/or their splice variants present on tumors." (PMID 35566020, 2022).
cancer (continued). "Although it has been known for more than 20 years that some cancers produce GHRH, it was only recently proposed that GHRH might function as an autocrine growth factor in neoplastic cells." (PMID 35566020, 2022). "The cancer cell growth could be stimulated by exogenous GHRH and, conversely, inhibited by GHRHR antagonists." (PMID 34599099, 2021). "Here, we show that GHRH antagonists of Miami (MIA) class, MIA-602 and MIA-690, are able to reduce the growth and promote cell death in hormone-secreting PA cell lines, through the inhibition of mechanisms implicated in tumorigenesis and cancer progression." (PMID 34439107, 2021). "Several peptide GHRH-R agonists and antagonists have been developed in the laboratory; we have utilized some of these to identify specific pathways and their effects regarding the actions of GHRH in lung inflammation, fibrosis, and cancer, as we describe in the section below." (PMID 33096674, 2020). "In human cancers, GHRH has been reported to function as an antocrine regulatory factor." (PMID 28032599, 2017). "Furthermore, human cancer cell lines treatment with growth hormone-releasing hormone (GHRH) antagonist MIA-602 show an increase in Cav-1 expression with a consequence of down-modulation of NF-κB." (PMID 28587148, 2017). "In different types of cancer, treatment with GHRH antagonist decreases cell migration and invasion." (PMID 28032599, 2017). "The presence of biologically active GHRH and its mRNA in various cancers and normal tissues suggests that locally produced GHRH might function as an autocrine growth factor for proliferation." (PMID 27494841, 2016). "This provides us a novel approach to treat cancer with GHRH antagonists." (PMID 27774107, 2016). "At this point, however, based upon findings in other GH-related long-lived mutants, we suspect that reduced incidence and/or delayed onset of cancer may have contributed to extended longevity of GHRH-KO mice." (PMID 24175087, 2013). "Further studies on GHRH antagonists may facilitate the development of new strategies for the treatment of resistant cancers." (PMID 22941871, 2012). "GHRH acts as an autocrine/paracrine growth factor in human cancers including breast." (PMID 22941871, 2012). "Given these conclusions, GHRH antagonists may provide effective treatment of patients suffering from difficult to treat or treatment resistant cancers such as TNBC." (PMID 22941871, 2012). "Previous studies showed that SV1 of GHRHR expressed in several cancers, may mediate the direct inhibitory effect of GHRH antagonists." (PMID 20509930, 2010). "This raised the issue of establishing the role of GHRH in these cancer lines." (PMID 18506184, 2008). "Our work supports the concept that GHRH functions as growth factor in human cancers." (PMID 18506184, 2008). "In an endeavour to develop new methods for cancer treatment, we developed the antagonists of GHRH." (PMID 18506184, 2008). "At the dose of 0.1 μM GHRH stimulated the proliferation rate of the cancer cell lines by 15–17%." (PMID 18506184, 2008). "In addition to this endocrine role, the biological actions of this 44-amino acid peptide are not limited to the pituitary–hypothalamic axis, since it was demonstrated that GHRH can function as an autocrine/paracrine growth factor in various extrapituitary tissues and several human cancers." (PMID 39201517, 2024). "GHRH may act as an autocrine and/or paracrine growth factor in cancers." (PMID 38957466, 2024). "Thus, the GHRH/GHRH-R pathway represents a suitable target for the treatment of cancer." (PMID 36232554, 2022). "A recent study investigated the diagnostic accuracy of the GHRH+Arginine test concluding that it should provide specific cut-off points depending on the pathological condition, such as congenital GHD, isolated GHD, multiple pituitary hormone defects and cancer survivors." (PMID 33716984, 2021).
cancer (continued). "While additional studies are needed to validate these findings across various experimental models, our results indicate that GHRH antagonists hold potential for development as adjuncts to radiotherapy in NSCLC and potentially other cancers." (PMID 40244089, 2025). "We searched a series of anti-cancer drugs that, in combination with MIA-602 or -690 GHRH antagonists, increase PCa/CRPC/NEPC cell death." (PMID 40427140, 2025). "GHRH and its receptor GHRHR (a member of the G protein-coupled receptor [GPCR] family) are also produced in multiple tissues and cancers to modulate cell proliferation and apoptosis, including PCa." (PMID 40427140, 2025). "The development of GHRH antagonists, particularly those in the MIA and AVR series, has provided new opportunities for cancer therapy and the treatment of other diseases." (PMID 39592529, 2024). "On the other hand, two hypothalamic hormones, i.e., growth hormone-releasing hormone (GHRH) and SST, are affected by the aging process, which in turn influences numerous age-related changes (including cancer)." (PMID 38540191, 2024). "Meanwhile, GHRH antagonists, particularly those in the MIA and AVR series, demonstrate potent antitumor activity by inhibiting cancer cell proliferation and downregulating growth factor pathways, while also exhibiting anti-inflammatory properties." (PMID 39592529, 2024). "We have previously shown that the use of GHRH antagonist MIA-602 successfully suppressed the growth of many human cancer cell lines, spanning more than 20 types of cancers." (PMID 37370714, 2023). "This is consistent with the antioxidative effects of GHRH antagonists, including MIA-602, demonstrated in different cell types and models of inflammation and cancer." (PMID 37649486, 2023). "In particular, the new generation GHRH antagonists of the Miami (MIA) series, MIA-690 and MIA-602, were shown able to inhibit growth of various human cancer cells and xenografts." (PMID 33510215, 2021). "In particular, the novel GHRH antagonists of the Miami (MIA) series, MIA-690 and MIA-602, were found to inhibit growth of different human cancer lines and xenografted into nude mice in microgram doses after subcutaneous administration." (PMID 31959947, 2020). "The goal of this review is to present and critically evaluate new findings regarding growth hormone-releasing hormone (GHRH) and its actions in the settings of lung inflammation, fibrosis, and cancer." (PMID 33096674, 2020). "It has been shown that the expressions of GHRH and GHRH-R SV1 and pituitary GHRH-R can be detected in many different types of human cancer." (PMID 28032599, 2017). "Our results also demonstrate the ability of a GHRH antagonist, MIA-602, to be a potential new treatment for drug resistant cancers." (PMID 25593995, 2014). "We also investigated the effect of GHRH and GHRH antagonists at two concentrations in MCF-7, MDA-MB-468, T47D, MDA-MB-435s, LNCaP and NCI H838 cancer cell lines." (PMID 18506184, 2008). "After the knocking down of GHRH expression, the proliferation rate of the T47D, MDA-MB-435s, MDA-MB-468, LNCaP, NCI H838 human cancer cell lines was decreased by 28.3, 85.9, 85.1, 51.8 and 48.4% respectively." (PMID 18506184, 2008). "Growth hormone-releasing hormone antagonist MZ-4-71 at the dose of 0.1 μM decreased the proliferation of T47D, MDA-MB-468, MDA-MB-435s, LNCaP and NCI H838 cancer cell lines by 37, 29, 32, 29, 28% respectively." (PMID 18506184, 2008). "After the transfection of the siRNA for GHRH, the proliferation rate of the MDA-MB-468 and MDA-MB-435s cancer lines was dramatically decreased by 85.1 and 85.9% respectively." (PMID 18506184, 2008). "Growth hormone-releasing hormone and the major SV1 of the full length GHRH receptor are expressed in surgical specimens of diverse human cancers as well as in a various human cancer cell lines." (PMID 18506184, 2008).
cancer (continued). "GHRH is a neuropeptide secreted from the hypothalamus that regulates the secretion of growth hormone (GH) from the pituitary, which then stimulates the liver to produce insulin growth factor 1 (IGF1), a potent mitogen for multiple cancers." (PMID 40427140, 2025). "GHRH antagonists, in addition to their indirect antitumor effects through the GHRH- pituitary GH-hepatic insulin-like growth factor-I (IGF-I) axis, were shown to directly inhibit the proliferation of human cancer cell lines in vitro." (PMID 35566020, 2022). "Both GHRH and GHRHR are present in lung, mammary, ovarian, endometrial, gastric, colorectal, ocular, prostatic, and pancreatic cancers." (PMID 34599099, 2021). "In order to determine whether GHRH agonist, MR-409, has an effect on the expression of IGF-1 in cancer cells, 16 human cancer cell lines were examined." (PMID 29983893, 2018). "Growth hormone-releasing hormone (GHRH) is a hypothalamic neuropeptide which regulates the synthesis and release of growth hormone by the pituitary and is an autocrine/paracrine growth factor for multiple human cancers." (PMID 22941871, 2012). "Thus GHRH antagonist MZ-5-156 at doses of 0.1 and 1 μM reduced the proliferation of T47D, MDA-MB-468, MDA-MB-435s, LNCaP and NCI H838 cancer cell lines by 30–35, 28–34, 33–40, 30–37, and 30–36% respectively." (PMID 18506184, 2008). "In addition, we examined the effect of GHRH and GHRH antagonists MZ-4-71, MZ-5-156 and JMR-132 at two dose levels on the proliferation rate of the cited cancer cell lines." (PMID 18506184, 2008). "The silenced cancer cell lines, lacking intrinsic GHRH, were still able to respond to exogenous GHRH, confirming the absence of possible toxic effects related to the transfections." (PMID 18506184, 2008). "Thus, the growth of various human cancers was suppressed without any involvement of the hypothalamic GHRH/pituitary GH/hepatic IGF-I axis." (PMID 20509930, 2010). "Both these cancer cell lines express SV-1 and because of its ligand-independent activity their proliferation rate continued to be stimulated in the absence of the intrinsic production of the GHRH." (PMID 18506184, 2008). "Thus GHRH could keep acting as a growth factor and the proliferation rate of all the cancer cell lines that were assayed may not reflect the conditions of a total absence of GHRH." (PMID 18506184, 2008). "The expression of the GHRH and its receptor SV1 in the breast, prostate and non-SCLC cancer cell lines examined suggested the presence of a stimulatory loop in those cells based on GHRH and its receptors." (PMID 18506184, 2008).
cardiovascular diseases (3 papers, 2025 to 2026). "Much experimental data supports that GHRH and its analogs may counteract maladaptive pathologic cardiovascular conditions at different functional levels in a broad spectrum of cardiovascular diseases." (PMID 39883351, 2025).
endocrine diseases (3 papers, 2017 to 2024). "DS can result in several endocrine disorders that may be linked to hypothalamic GHD resulting from GHRH–GH–IGF-1 axis impairment." (PMID 39027638, 2024). "Twenty-six patients (83.87%) who presented normal IGF-1 concentrations and a normal response to the GHRH + arginine test were discharged from follow-up for a reduced risk of evolving into endocrinopathy, whereas endocrine follow-up was recommended for the five patients with subnormal GH stimulation." (PMID 30678118, 2019). "In keeping with this, phase 1 clinical trials of a long-acting growth hormone-releasing hormone agonist peptide for the potential treatment of metabolic/endocrine diseases as well as HIV have so far been successful." (PMID 28931678, 2017).
infection (3 papers, 2017 to 2021). The state of being infected such as from the introduction of a foreign agent such as serum, vaccine, antigenic substance or organism. "We incorporated into the viral injection the two key neuroendocrine hormones driving somatotroph proliferation, GHRH and ghrelin, to reinforce somatotroph-specific infection." (PMID 34588620, 2021).